FAM76A (family with sequence similarity 76 member A)
Synonyms: MGC34648
Tractability: PROTAC: its protein half-life has been measured.
Gene: Protein-coding gene on chromosome 1 (27,725,961 to 27,763,116, forward strand). Ensembl gene ENSG00000009780.
Subcellular location (Human Protein Atlas): Cytosol; Nucleoplasm
Gene Ontology:
Cellular component: nucleoplasm; nuclear speck
Genetic constraint (gnomAD): Loss-of-function variants: 28 observed, 34.36 expected, observed/expected ratio (o/e) 0.81, 90% interval 0.6 to 1.12. The upper end of that interval is the gene's LOEUF score, 1.12, which puts it in group 4 of 6, group 1 being the genes least tolerant of losing a copy. Missense variants: 261 observed, 331.18 expected, observed/expected ratio (o/e) 0.79, 90% interval 0.71 to 0.87. Synonymous variants: 132 observed, 117.5 expected, observed/expected ratio (o/e) 1.12, 90% interval 0.97 to 1.3.
Homologues: Orthologues: chimpanzee FAM76A (99% identical), macaque FAM76A (99% identical), rabbit FAM76A (99% identical), guinea pig FAM76A (99% identical), dog FAM76A (99% identical), pig FAM76A (99% identical), mouse Fam76a (98% identical), rat Fam76a (89% identical), Drosophila melanogaster CG4452 (43% identical), Caenorhabditis elegans K04F10.7 (30% identical). Paralogues in human: FAM76B (74% identical), SENP8 (10% identical).
Diseases named in the same sentence as FAM76A in open-access papers:
FAM76A is named in the same sentence as 1 disease in open-access papers, as found by Europe PMC text mining. Sharing a sentence is not in itself a finding about the gene and the disease. The quoted sentences say what the papers report.
ovarian carcinoma (3 papers, 2020 to 2022). A malignant neoplasm originating from the surface ovarian epithelium. "GSEA was performed to determine a potential mechanism for HBS1L and FAM76A involved in ovarian cancer." (PMID 32998774, 2020). "However, how the WTAP-HBS1L/FAM76A axis plays a role in ovarian cancer progression needs further experimental verification." (PMID 32998774, 2020). "WTAP functions as an oncogenic factor that promotes the progression of ovarian cancer in which WTAP-HBS1L/FAM76A axis may be involved." (PMID 32998774, 2020). "At the same time, the high expression of FAM76A and HBS1L also suggested poor survival in ovarian cancer patients." (PMID 32998774, 2020).